APOE (apolipoprotein E)
Diseases named in the same sentence as APOE in open-access papers (continued):
Sharing a sentence is not in itself a finding about the gene and the disease.
Alzheimer disease (continued). "The APOE gene has three alleles, epsilon 2, epsilon 3, and epsilon 4, with varying risks of Alzheimer’s disease." (PMID 37240173, 2023). "The mitochondrial protein network modulating APOE expression includes proteins encoded by prioritized genes within Alzheimer’s disease risk loci necessary for electron transport chain complex I assembly and function." (PMID 37171075, 2023). "The association of the APOE e4 allele with increased Alzheimer’s Disease (AD) risk is well documented and APOE e4 has also been shown to be associated with increased severity of CTE pathology." (PMID 36895005, 2023). "We ran additional models controlling for cardiovascular risk and genetic risk of Alzheimer’s disease, defined as a carrier of at least one apolipoprotein E (APOE) ε4 allele." (PMID 37377978, 2023). "Extraordinarily relevant to the associations between cardiovascular morbidity and Alzheimer’s disease is the report of Habenicht and collaborators associating a C1q-ApoE complex in intimal arterial lesions and human amyloid plaques." (PMID 37371506, 2023). "It has been reported that the risk for Alzheimer’s disease associated with APOE Ɛ4/Ɛ4 was higher in men than in women." (PMID 36617573, 2023). "The APOE genotype also accounts for most of the risk related to Alzheimer’s disease development, with ε4 being the most involved isoform in this case." (PMID 37185708, 2023). "This genetic association study assesses associations between apolipoprotein E and Alzheimer disease risk across age, sex, race and ethnicity, and global population ancestry." (PMID 37930705, 2023). "Although aging and apolipoprotein E (APOE) ε4 allele have been documented as two major risk factors for late‐onset Alzheimer's disease (LOAD), their interaction and potential underlying mechanisms remain unelucidated." (PMID 37594184, 2023). "Alzheimer’s disease patients who had a homozygous mutation in both APOE alleles scored worse on difficult memory discrimination." (PMID 36981525, 2023). "Since other factors such as the presence of some genetic variants in the ApoE gene, mainly ApoE 4, are associated with the development of Alzheimer’s disease, this polymorphism was measured in these subjects." (PMID 36839291, 2023). "APOE, one of theour top multivariate longevity genes, has been associated with coronary artery disease, Alzheimer’s disease, and longevity." (PMID 37076473, 2023). "A systematic investigation of the gene networks firstly revealed that the Apolipoprotein E4 (ApoE4) gene plays a central role among genes associated with Alzheimer’s disease." (PMID 40809494, 2023). "Interactions with Alzheimer’s disease (AD) risk factors, including apolipoprotein E4 (APOE4) genotype, TOMM40 genotype, and family history of AD, were also assessed." (PMID 37571327, 2023). "The ε2 allele of apolipoprotein E (ε2) has neuroprotective effects against beta-amyloid (Aβ) pathology in Alzheimer’s disease (AD)." (PMID 37511008, 2023). "In humans, the APOE gene exists as three polymorphic alleles (APOE2, APOE3, and APOE4), where APOE4 is the strongest genetic risk factor for Alzheimer’s disease (AD)." (PMID 37605285, 2023). "APOE-ε4 allele[s] is associated with a higher risk of developing Alzheimer's disease (AD) and its earlier onset, making it a critical focus in observational studies on AD or dementia." (PMID 39081988, 2023). "Alzheimer's Disease (AD) is a heterogeneous disease that disproportionately affects women and people with the APOE-ε4 susceptibility gene." (PMID 37333001, 2023). "The apolipoprotein E ɛ4 allele (APOE4) is universally acknowledged as the most potent genetic risk factor for Alzheimer's disease (AD)." (PMID 37646624, 2023). "A major risk factor for Alzheimer’s disease (AD), the apolipoprotein E4 (APOE4) allele, is implicated in lipid metabolism and is associated with metabolic and oxidative stress that can result from dysfunctional mitochondria." (PMID 36847010, 2023).
Alzheimer disease (continued). "Among risk factors for AD, such as age, sex, and education, the APOE e4 allele is the strongest known genetic risk factor for Alzheimer's disease despite unclear neurostructural substrates." (PMID 36864910, 2023). "Prior studies have yielded mixed findings concerning the association between apolipoprotein E(APOE)-ε4 and serum lipids in patients with Alzheimer’s disease (AD) and healthy individuals." (PMID 38002514, 2023). "To develop a neural spheroid Alzheimer’s disease (AD) drug screening platform, we used GABAergic neurons that were genetically engineered to carry the apolipoprotein e4/4 (APOE4) allele, a genotype known to increase the risk for AD24,25." (PMID 38017066, 2023). "The APOE4 variant of apolipoprotein E (apoE) is the most prevalent genetic risk allele associated with late‐onset Alzheimer's disease (AD)." (PMID 37155564, 2023). "Apolipoprotein E4 (APOE4) is the strongest known genetic risk factor for late-onset Alzheimer’s disease (AD)." (PMID 37118426, 2023). "APOE variants are one of the major genetic risk factors of Alzheimer’s disease (AD) and cholesterol has been associated with AD development downstream of Aβ and Tau pathology." (PMID 37333177, 2023). "APOE genotype is a risk factor for AD, and APOE-ε 4 allele is considered to be the strongest genetic modifier of late-onset Alzheimer's disease." (PMID 37213538, 2023). "Apolipoprotein E (APOE) is the single greatest genetic risk factor for late onset Alzheimer's disease (AD)." (PMID 38115077, 2023). "How do associations of apolipoprotein E (APOE) genotypes with late-onset Alzheimer disease (AD) risk differ across age, sex, and population ancestry?" (PMID 37930705, 2023). "The Apolipoprotein E (APOE) epsilon (ε) 4 allele is a well-established risk factor for late-onset Alzheimer’s disease (AD)." (PMID 37680541, 2023). "Apolipoprotein E4 (APOE4) is the strongest genetic risk factor for Alzheimer's disease (AD), the most common form of dementia characterized by extracellular beta-amyloid plaques, intraneuronal tau tangles, and neurodegeneration." (PMID 37704738, 2023). "The most prevalent genetic risk factor for Alzheimer’s disease (AD) is Apolipoprotein E (ApoE), a gene located on chromosome 19 that encodes three alleles (e2, e3, and e4) that give rise to the ApoE subtypes E2, E3, and E4, respectively." (PMID 37333457, 2023). "Both sporadic and familial forms of Alzheimer’s disease (AD) are associated with the presence of the E4 allele of Apolipoprotein E (APOE)." (PMID 37337279, 2023). "Early studies have reported that APOE is strongly associated with brain atrophy and cognitive decline among healthy elders and Alzheimer’s disease (AD)." (PMID 37323144, 2023). "Apolipoprotein E (ApoE) is associated with Alzheimer’s disease (AD) and cognitive dysfunction in elderly individuals." (PMID 37396111, 2023). "The apolipoprotein E gene ε4 allele (APOE-ε4) is the main genetic risk factor for late-onset Alzheimer’s disease (AD)." (PMID 38115150, 2023). "Among these single nucleotide polymorphisms, rs429358, located in APOE gene was associated with diverse age-related diseases, such as Alzheimer’s disease, coronary artery disease, age-related degenerative macular diseases, and cognitive decline." (PMID 36276968, 2022). "We also supported previous findings that APOE-ɛ4 increases risk for Alzheimer’s disease both upstream and downstream of amyloid pathology." (PMID 35425899, 2022). "APOE Ɛ4 allele has been particularly investigated in neurodegenerative and cognitive impairment diseases, and indeed, severe COVID-19 and Alzheimer’s disease share common genetic and metabolic pathways via the OAS1 gene and many risk factors strongly overlap." (PMID 36531241, 2022). "In this study we identify a protective locus for the ApoE ε4 allele that lowers the risk for African carriers of the ApoE ε4 allele to get Alzheimer disease from an odds ratio of 7.2 to 2.1." (PMID 35788729, 2022).
Alzheimer disease (continued). "Genome-wide association studies revealed that APOE is a genetic risk factor for late onset Alzheimer’s disease." (PMID 36077289, 2022). "The most important genetic risk factor for late-onset Alzheimer’s disease is the ɛ4 allele of apolipoprotein E." (PMID 36077172, 2022). "Early-onset Alzheimer's disease is more likely when ApoE-4 is expressed, which is also linked to diabetes." (PMID 36505102, 2022). "Background: the apolipoprotein e4 allele (APOE4) constitutes an established genetic risk factor for Alzheimer’s Disease Dementia (ADD)." (PMID 36648906, 2022). "Fourth, we do not have information on the Apolipoprotein E (ApoE) genetic variants, with ApoE being the main apolipoprotein expressed in the brain and a known genetic variant that is strongly associated with Alzheimer's Disease." (PMID 36247924, 2022). "The ApoE (apolipoprotein E) gene variations that were linked to the onset of Alzheimer’s disease were examined using DSNP, which either determined the predisposition to their origination or were implicated in the development of diseases." (PMID 36551139, 2022). "Functional gene set enrichment analysis showed significant correlation with the KEGG Alzheimer’s Disease pathway as well as APOE-associated pathways such as HALLMARK Adipogenesis." (PMID 36271092, 2022). "Our findings further support earlier observations that HDL particles are implicated in Alzheimer’s disease pathology and highlight, for the first time, that there is an APOE genotype-dependent relationship that merits further study." (PMID 35884800, 2022). "The ε4 allele is a genetic risk factor for Alzheimer’s disease (AD); therefore, the vast majority of APOE research focuses on its role in AD pathology." (PMID 36018414, 2022). "﻿Although the ε4 allele of APOE gene is the strongest genetic risk factor for late-onset Alzheimer’s disease, the exact mechanism mediating APOE ε4 pathological effect remains elusive." (PMID 35702728, 2022). "Even disorders highly correlated to apoE genotype, such as the E4 allele and its associated risk for Alzheimer’s disease and cardiovascular disease are influenced by race and ethnicity." (PMID 35347119, 2022). "Apolipoprotein E (ApoE), one of the genes associated with Alzheimer’s disease, has two SNPs, resulting in three alleles, E2, E3 and E4." (PMID 35271014, 2022). "Future studies exploring associations between cardiovascular risk and Alzheimer’s disease -related outcomes should consider stratifying by sex and APOE ɛ4." (PMID 35233525, 2022). "For example, having the Apolipoprotein E allele is the strongest risk factor (after aging) for late-onset Alzheimer’s disease in the European ancestry population." (PMID 35731202, 2022). "It is of interest that a proxy of rs429358, part of the established APOE Ɛ4 risk allele for Alzheimer’s disease, is associated with lower LST." (PMID 36071172, 2022). "ApoE ɛ2, ɛ3, and ɛ4 alleles strongly alter, in a dose-dependent manner, the likelihood of manifesting Alzheimer's disease and cerebral amyloid angiopathy." (PMID 35061102, 2022). "Eight proteins were associated with all-cause dementia outcome and their pQTLs were centered within 500 kilobases (kb) from the APOE gene, one of the strongest genetic risk factors for late-onset Alzheimer’s disease reduced." (PMID 37118290, 2022). "Cumulative evidence suggests that the ε4 allele of APOE is the major genetic risk factor for Alzheimer’s disease." (PMID 36613677, 2022). "The human apolipoprotein E4 isoform (APOE4) is the strongest genetic risk factor for late-onset Alzheimer's disease (AD), and lysosomal dysfunction has been implicated in AD pathogenesis." (PMID 34982109, 2022). "Herein we provide a brief synopsis highlighting key salient findings on mechanisms by which apoE polymorphisms influence Alzheimer’s disease risk." (PMID 36077289, 2022). "The risk of Alzheimer's disease in APOE ε4 carriers increased with white wine consumption vs. red wine consumption." (PMID 35634389, 2022).
Alzheimer disease (continued). "Recent studies have shown that the APOE genotype is almost solely responsible for amyloid deposition whereas other components of Alzheimer's disease (AD) genetic risk contribute to the occurrence of dementia in the context of amyloid deposition." (PMID 35977442, 2022). "We provide evidence for the first time of APOE genotype-specific alterations in HDL particles in Alzheimer’s disease and an association between HDL function, size, and cognitive function." (PMID 35884800, 2022). "Perhaps a variable at the personal level that was not considered in our study was genetics; for example, we know that the APOE-e4 gene is associated with a higher risk of Alzheimer dementia." (PMID 35330040, 2022). "APOE encodes a cholesterol transporter, and the ε4 allele is associated with higher circulating cholesterol levels, ß-amyloid burden, and risk of Alzheimer’s disease." (PMID 35404972, 2022). "SNPs in ABCA7 confer the largest genetic risk for Alzheimer’s Disease (AD) in African Americans (AA) after APOE ε4." (PMID 36421824, 2022). "Apolipoprotein E (APOE) alleles impact multiple facets of the human condition, ranging from Alzheimer’s disease (AD) to cardiovascular disease, metabolic syndrome, obesity, fertility and longevity (reviewed in Ref.1)." (PMID 35115575, 2022). "The method was also applied to the diagnosis of SNPs, such as ApoE (apolipoprotein E), which is a risk factor for Alzheimer’s disease." (PMID 35271014, 2022). "ApoE occurs under several isoforms, the e4 of which is a strong genetic risk factor of Alzheimer’s disease." (PMID 35663580, 2022). "This study identified a new African-ancestry specific locus that reduces the risk effect of ApoE ε4 for developing Alzheimer disease." (PMID 35788729, 2022). "Out of the many, one key genetic risk component responsible for late-onset Alzheimer's disease is Apolipoprotein-E4 (APOE4), which delays the transport of Aβ from the brain, causing blood-brain barrier breakdown." (PMID 35621297, 2022). "One participant reported having been identified as a carrier of the APOE ε4 allele, associated with an elevated risk of late-onset Alzheimer’s disease (APOE ε4 allele represents about 5–30% of the APOE alleles in European populations)." (PMID 35084702, 2022). "A meta-analysis of genome-wide association studies (GWAS) of people of European ancestry identified risk loci associated with late-onset Alzheimer's disease, in addition to the widely known ε4 allele of the apolipoprotein E (APOE) gene." (PMID 35711612, 2022). "Serum levels of APOE have been associated with increased risk of developing Alzheimer’s disease and cognitive impairment." (PMID 36048760, 2022). "Among the three major APOE alleles, ε4 allele increases while ε2 allele decreases Alzheimer’s disease risk compared to the most common ε3 allele." (PMID 36077289, 2022). "Alzheimer’s disease (AD) is the most common form of dementia and the leading risk factor, after age, is possession of the apolipoprotein E epsilon 4 allele (APOE4)." (PMID 35806110, 2022). "Human induced pluripotent stem cell (hiPSC)–based models of the brain will be key to unraveling the role of APOE ɛ4 in the interconnected cellular changes underlying Alzheimer’s disease." (PMID 36167428, 2022). "For instance, a large proportion of Alzheimer’s disease risk heritability is conferred by the common allele of APOE e434–36." (PMID 35710731, 2022). "Variants in the cholesterol-binding protein, apoE have been suggested to increase the risk of cardiovascular disease and Alzheimer’s disease." (PMID 35159267, 2022). "Apolipoprotein E (APOE), encoding a major lipid transport molecule within the central nervous system, and variants that are associated strongly with Alzheimer's disease risk, was upregulated in this dataset." (PMID 35348588, 2022). "Apolipoprotein-E (APOE) polymorphisms, particularly APOE e4, are significant risk factors for neurological disorders, such as Alzheimer’s disease." (PMID 35942230, 2022).
Alzheimer disease (continued). "In Alzheimer's disease (AD), pericyte degeneration, for instance, is more likely in patients who carry the ε4 allele of apolipoprotein E (APOE*ε4)." (PMID 35755780, 2022). "Genetic changes in the apolipoprotein E (APOE) gene have proven to be a potent risk factor for late-onset Alzheimer's disease, apart from aging." (PMID 36258952, 2022). "The high number of APO and LRP proteins in this network potentially drives the significant association with Alzheimer’s Disease, for which genotype of APOE is the main risk factor." (PMID 35576218, 2022). "One familial risk factor is the allele of apolipoprotein E (APOE*ε4) associated with Alzheimer's disease (AD)." (PMID 35755780, 2022). "Apolipoprotein ε4 (APOE ε4) is the most significant genetic risk factor for late-onset Alzheimer’s disease (AD)." (PMID 36550123, 2022). "Previous studies have reported that mutation of Apolipoprotein E (APOE) and regulation of its expression have an important connection with Alzheimer’s disease (AD) dementia because of the pivotal role of APOE in lipoprotein metabolism in the brain." (PMID 35720695, 2022). "While the association between the LDL-PGS and the risk for Alzheimer’s disease was slightly attenuated after removing the ApoE locus (OR = 1.23 vs. 1.36 per SD PGS increase), the association remained significant (p-value = 2.51 × 10−21)." (PMID 36575460, 2022). "The apolipoprotein E4 (APOE4) genotype is one of the strongest genetic risk factors for Alzheimer’s disease (AD), and is generally believed to cause widespread pathological alterations in various types of brain cells." (PMID 35691989, 2022). "APOE e4 has been the focus of apolipoprotein E genotype (APOE) investigation since Allen Roses discovered its association with Alzheimer’s disease (AD) in 1993." (PMID 35912085, 2022). "APOE is known to be associated with Alzheimer’s disease and is located in the lifespan-related loci of the turquoise killifish." (PMID 35910227, 2022). "We extended our analysis to knock-in mouse models of APOE alleles and found the same effect for the late onset Alzheimer's disease risk allele ε4." (PMID 34842276, 2022). "Apolipoprotein E (ApoE) genotyping has been shown to have diagnostic value in the evaluation of cardiovascular diseases and neurodegenerative disorders such as Alzheimer’s disease." (PMID 36380282, 2022). "Several excellent review articles with comprehensive discussions on the relationship between APOE polymorphisms and Alzheimer’s disease risk have been published recently." (PMID 36077289, 2022). "For example, about 25% to 30% of the population carries the APOE ε4 allele, which increases the risk of Alzheimer’s disease in a dose-dependent way." (PMID 35242026, 2022). "The Apolipoprotein (APOE) gene has been linked to the risk and age of onset of Alzheimer’s Disease (AD)." (PMID 36139002, 2022). "The APOE variant (rs439401, on chromosome 19) is frequently reported in association with lipid traits, and in some studies in connection with Alzheimer’s disease." (PMID 36088317, 2022). "We focused on the genetic variants outside of the APOE locus that have been shown to be associated with Alzheimer’s disease and, separately, with CAD genetic variants." (PMID 36523268, 2022). "The noxious effects that the ɛ4 allele of the apolipoprotein E gene (i.e., APOE4) exerts on brain functioning have been associated with impaired cognitive performance and an increased risk of late-onset Alzheimer’s disease (AD)." (PMID 34591236, 2022). "Strong associations between ApoE ε4 and Alzheimer disease risk have been confirmed worldwide, but there is variability in the effect size across populations." (PMID 35788729, 2022). "Specifically, we investigated the extent to which APOE modulated the association between mIns concentration and both hallmarks of Alzheimer’s disease pathology, Aβ and tau, quantified by 18F-flutemetamol PET and 18F-RO948 PET, respectively." (PMID 35702728, 2022).